PIK3CA (phosphatidylinositol-4,5-bisphosphate 3-kinase catalytic subunit alpha)
Diseases named in the same sentence as PIK3CA in open-access papers (continued):
Sharing a sentence is not in itself a finding about the gene and the disease.
endometrial cancer (continued). "Mutations in multiple oncogenes including KRAS, CTNNB1, PIK3CA and FGFR2 have been identified in endometrial cancer." (PMID 22383975, 2012). "Among the included genes and mutations, we have identified and validated KRAS, PIK3CA and FGFR2 to be the most frequently mutated oncogenes in endometrial cancer." (PMID 23300780, 2012). "Our previous screening of a smaller number of endometrial cancer patients identified somatic mutations in FGFR2, KRAS, PIK3CA, PTEN, PT53 and CTNNB1." (PMID 23300780, 2012). "We then examined the correlation of these expression patterns and the mutation status of PTEN, PIK3CA and KRAS, on the basis of our previous data of the frequency of such mutations in an overlapped population of endometrial cancers." (PMID 20664599, 2010). "While coincident mutations in these genes have previously been reported in cancers of the large intestine, PIK3CA and KRAS mutations have typically exhibited a mutually exclusive pattern of occurrence in endometrial cancer." (PMID 19924296, 2009). "Consequently, mutation rates for PIK3CA are at least 10-fold higher than PIK3CB/PIK3CD/PIK3CG in solid tumours such as breast and endometrial cancer (TCGA Research Network)." (PMID 40360883, 2025). "PIK3CA, which encodes the catalytic subunit p110α of phosphoinositide 3-kinase (PI3K), is one of the most frequently mutated genes in various cancers, including endometrial cancer." (PMID 40072110, 2025). "In ovarian and endometrial cancers, ARID1A mutations often co-occur with alterations in the PI3K/AKT (phosphoinositide 3-kinase/activated protein kinase) pathway genes KRAS (Kirsten rat sarcoma virus), PIK3CA, and PTEN (phosphatase and tensin homolog)." (PMID 39684461, 2024). "In endometrial cancer, ARID1A, PTEN, and PIK3CA were commonly mutated across all groups." (PMID 38282550, 2024). "For example, the presence of a PTEN mutation, especially when mutated concurrently with a PIK3CA and KRAS mutation, may predict sporadic MMR deficient endometrial cancer; the wild-type status of PTEN may be associated with LS-associated endometrial cancer." (PMID 35884469, 2022). "In addition, the lower mutation rates of TTN, PTEN, PIK3CA and ARID1A have been identified as possible risk factors in endometrial cancer." (PMID 35893039, 2022). "Mutations in PIK3CA, PIK3R1, and KRAS also occur at high frequency in endometrial carcinoma." (PMID 34831139, 2021). "PIK3CA was identified as one of the most commonly mutated “driver genes” in endometrial tumors and, accordingly, multiple PI3KCA, AKT and mTOR targeted inhibitors are currently in Phase I-III clinical trials against solid tumors including endometrial cancer." (PMID 31934607, 2020).
endometrial cancer (continued). "Of these, 2 INDELs are identified in dbCID in association with cancer (PTEN frameshift c.950_953delTACT previously reported with endometrial cancer and PIK3CA non-frameshift c.325_327delGAA previously associated with melanoma)." (PMID 33256706, 2020). "In endometrial carcinoma, PIK3CA amplifications, but not PIK3CA mutation, were associated with older age." (PMID 32961530, 2020). "On the other hand, the PTEN and PIK3CA networks generated through our analysis of endometrial carcinoma datasets highlight the underappreciated divergence in signaling changes that may occur as a result of mutations in these genes." (PMID 31253832, 2019). "Moreover we showed that two PIK3CA mutations or the coexistence of PIK3CA and PTEN mutations are needed to influence endometrial cancer prognosis." (PMID 29876005, 2018). "Most molecular studies in endometrial cancer have focused on the most common form, uterine endometrioid carcinoma (UEC), which is primarily driven by PTEN loss and mutations in FGFR2, ARID1A, CTNNB1, PIK3CA, PIK2R1, and KRAS." (PMID 26170901, 2015). "However, oncogenic alterations of PTEN and PIK3CA are often found in ovarian and endometrial cancers." (PMID 26469226, 2015). "In endometrial cancer, the constitutive activation of the phosphatidylinositol 3-kinase (PI3K) pathway is induced by various types of alternations, including frequent mutations of K-Ras (10–20%), PIK3CA (25–36%), AKT (2%), and PTEN (34–56%)." (PMID 24625059, 2014). "PIK3CA activation is reported in 26–36% of endometrial carcinoma and may coexist with PTEN (15–27%) and KRAS mutations suggesting that the PIK3CA mutations cooperate with these alterations in malignant transformation." (PMID 20368795, 2010). "We reported earlier that PIK3CA mutations frequently coexist with other PI3K-activating alterations in breast (with HER2 and HER3) and endometrial cancers (with PTEN and K-Ras), and that mutant p110α combined with mutant Ras efficiently transformed immortalised human mammary epithelial cells." (PMID 19491896, 2009). "In this study, we screened 89 endometrial carcinoma specimens and 12 endometrial carcinoma cell lines for mutations in Akt1 (E17K) and analysed whether AKT1 mutations coexist with any mutations in PTEN, PIK3CA and K-Ras." (PMID 19491896, 2009). "Notably, patients with endometrial cancer exhibited a high proportion of PTEN mutations when they had multi‐PIK3CA mutations as opposed to only a single mutation, although the difference was not significant." (PMID 39054873, 2024). "As we suggest in this paper, a PIK3CA or PTEN status may provide additional therapeutic implications in advanced or metastatic endometrial cancer, considering the relatively high frequency of PIK3CA mutation or PTEN loss, regardless of four molecular groups." (PMID 37835582, 2023). "A specific endometrial cancer organoid line was most sensitive to everolimus (an inhibitor of mammalian target of rapamycin mTOR), which suggested a strong dependence on the PI3K-AKT pathway and was in line with mutations in the pathway’s signaling mediators (PTEN, PIK3CA, AKT1)." (PMID 36699015, 2022). "The MET/PIK3CA and MET/KRAS co-mutation may have biological impacts on endometrial cancer cells." (PMID 34439385, 2021). "PIK3CA is the second most mutated gene, with overall frequencies of 25% of tumours according to the Catalog of Somatic Mutations In Cancer (COSMIC, v86) as well as of 51% and 53% in TCGA-UCEC (release 13) and the TCGA endometrial cancer genomic data, respectively (B and Figure A1)." (PMID 30544563, 2018). "PIK3CA mutations did not influence disease specific endometrial carcinoma survival." (PMID 28860563, 2017).
endometrial cancer (continued). "Although transcriptional signature pattern according to histologic grade did not identify any distinct subgroups linking any of the mutations to phenotype, PIK3CA, KRAS and FGFR2 mutations may still be of relevance for targeting novel therapeutics in endometrial cancer." (PMID 23300780, 2012). "The potential targets for targeted treatment of endometrial cancer (KRAS, PIK3CA, MLH1, MSH6, POLE, PTEN) showed more significant changes in the supernatant of vaginal lavage fluid." (PMID 41602422, 2026). "For example, endometrial cancer is characterized by intrachromosomal amplification of ESR1, KRAS, PIK3CA, ERBB2, TERC, MYC, CCNE1." (PMID 41415205, 2025). "In endometrial carcinoma, upregulated SNORD60 binds FBL, catalyzes the 2′-O-Me modification of PIK3CA mRNA and modulates the PI3K/AKT/mTOR signaling pathway to promote the development of endometrial cancer." (PMID 39605984, 2024). "Miransertib is an AKT1 inhibitor that has been combined with anastrozole in women with PIK3CA and AKT1-mutant ER-positive endometrial cancer and EOC." (PMID 37626654, 2023). "In endometrial cancer, genomic alterations are common in the phosphatidylinositol-3 kinase (PI3K) pathway (such as PTEN, PIK3CA, and PIK3R1) and the receptor tyrosine kinase/RAS pathway." (PMID 38201563, 2023). "Among them, the key players are PIK3CA, BRAF, and epidermal growth factor receptor (EGFR), which activate various tumor cell signaling pathways in endometrial cancer cells." (PMID 35264951, 2022). "The correlation between PIK3CA and PTEN has also been reported previously in endometrial cancer in a cohort of cases from Japan." (PMID 33920951, 2021). "Patients with PIK3CA-altered advanced cancer were treated with the p110α selective inhibitor Alpelisib (BYL719) and one patient with endometrial cancer showed a complete response and another showed a partial response to treatment (, NCT01219699)." (PMID 30544563, 2018). "Another study made similar experiments, but this time using 13 endometrial cancer cell lines (possessing at least one alteration of PTEN, PIK3CA or KRAS) and xenografts in nude mice in vivo." (PMID 28008141, 2017). "We examined the antitumor effect of NVP-BEZ235—a dual PI3K/mTOR inhibitor—and RAD001—an mTOR inhibitor—in 13 endometrial cancer cell lines, all of which possess one or more alterations in PTEN, PIK3CA, and K-Ras." (PMID 22662154, 2012). "There were two genetic features found to be predictive of shorter survival, namely FBXW7 in endometrial cancer and PIK3CA in glioma, which were not reported before." (PMID 40353995, 2025). "Whole genome and target sequencing of endometrial glands have identified extensive clonal expansions in individuals without endometrial cancer, with more frequent somatic mutations seen in KRAS and PIK3CA specifically." (PMID 36311816, 2022). "High frequency of coexistent mutations of PIK3CA and PTEN genes has been reported previously in endometrial carcinoma but not in GC." (PMID 32610572, 2020). "As previously shown in endometrial cancers, increased pAKT was also found in tumors with ARID1A/BAF250a loss when both PIK3CA mutation or PTEN loss were absent." (PMID 24559118, 2014). "Thus, PIK3CA mutation alone might not be a good biomarker in endometrial cancer." (PMID 22662154, 2012).
endometrial cancer (continued). "We recently reported that combination treatment with a PI3K/mTOR inhibitor, SAR245409 (voxtalisib), and a MEK inhibitor, pimasertib, showed synergistic antitumor effects in 6 out of 12 endometrial cancer cell lines and that mutational statuses of KRAS, PIK3CA, and PTEN were not involved." (PMID 27102436, 2016). "On the contrary, in non-inmunogenic endometrial cancer, recent studies have associated alterations such as CTNNB1 or PIK3CA genomic aberrations and CMYC amplification, with a low neoantigen load, that could lead to predict poor effects of immunotherapy response." (PMID 36010253, 2022). "Mutations in PI3 kinase pathway are extremely common in tumors: for example, nearly 80% of cases of endometrial carcinoma (non-ultramutated samples) have inactivating mutations in PTEN and 45% of human luminal A breast tumors harbor activating mutations in PIK3CA." (PMID 26809587, 2016).
colon carcinoma (185 papers, 2005 to 2025). "Case Presentation: We present a case report of a 68-year-old female patient with KRAS G12D and PIK3CA mutations who was diagnosed with stage IV-C colon cancer." (PMID 40710850, 2025). "The phase II clinical trial of CB-839 and capecitabine in patients with PIK3CA-mutated colon cancer reported here had 21.8% of patients surpassing 6 months PFS, which did not meet its prespecified objective of 25% of patients with over 6 months PFS." (PMID 38194275, 2024). "Studies have found that cationic micelle delivery of multi-epitope candidate vaccines derived from tumor-associated antigens (including PIK3CA) can lead to regression of established CT26 colon tumors in mice." (PMID 39555098, 2024). "The primary colon tumor was used for sequencing in 70% (590/846) of cases with multi-hit PIK3CA mutations and a metastatic site was used in 30% (256/846) of the cases." (PMID 39401325, 2024). "Colon cancer cell lines showed increased resistance to cetuximab when PTEN expression is lost or PIK3CA is mutated, and an even higher degree of resistance when any of these alterations is concurrently present with RAS/BRAF mutations." (PMID 38731914, 2024). "Further analysis was performed on the underlying correlation of APOA5 in L-OHP resistance of PIK3CA-E545K mutant colon cancer." (PMID 38848145, 2024). "Specifically, among patients with colon cancer, only 6 out of 617 cases (0.96%) with multiple PIK3CA mutations exhibited PTEN mutations compared with 6 out of 90 cases (6.67%) with a single PIK3CA mutation." (PMID 39054873, 2024). "The authors found that RAB3C overexpression induces dystrophin expression to promote vesicle formation and packaging for increased exocytosis, is related to drug resistance and is correlated with PIK3CA/KRAS mutation status in colon cancer." (PMID 36652260, 2023). "To further test this possibility, we utilized LS174T human colon tumor cells, which harbor a PIK3CA mutation that enhances COX-2 expression and signal transduction and tumor proliferation through autocrine signaling of PGE2 through EP2 and EP4 receptors." (PMID 37559947, 2023). "One phase 3 clinical trial involves the use of aspirin as an adjuvant component in stages II and III PIK3CA-mutated colon cancer patients." (PMID 35565237, 2022). "From right- to left-sided colon cancer, a gradual decrease in PIK3CA mutation rates from as high as 21–25% down to 8–9% has been observed in the literature." (PMID 35203549, 2022). "In women, a role of KRAS mutations in the etiological pathway between adiposity and colon cancer is suggested, and of PIK3CA mutations between physical activity and colon cancer." (PMID 35546360, 2022). "We isolated primary cells from a colon cancer tissue harboring PIK3CA E545K mutation and further confirmed that circLHFPL2 inhibits CRC progression by downregulating PTEN." (PMID 35619132, 2022). "There are currently ongoing clinical trials (mostly focused on colon cancer patients harbouring PIK3CA mutations) that will look into this matter in detail." (PMID 32977434, 2020). "Both KRAS and PIK3CA mutations were associated with poor prognosis and chemoresistance of colon cancer patients." (PMID 33197880, 2020). "According to the Cosmic database, PIK3CA is mutated in 18% of colon cancers and in 10% of rectal cancers." (PMID 32580435, 2020). "Apart from KRAS status, and resistance to anti-EGFR therapy, mutations in PIK3CA are associated with proximal colonic tumors, and adverse outcomes for patients with BRAF wild-type tumors." (PMID 30736475, 2019). "In some cases of colon cancer, PIK3CA mutation was estimated to have occurred at least a decade before cancer diagnosis." (PMID 31374965, 2019).